IL4 (interleukin 4)
Diseases named in the same sentence as IL4 in open-access papers (continued):
Sharing a sentence is not in itself a finding about the gene and the disease.
infection (continued). "During the evolution of the infection, the population of IL-4-producing CD4+ T-cells increased during the Lb infection and decreased during the La infection." (PMID 27073297, 2016). "The IL4 expression followed the similar trend: it was upregulated approximately 9 fold by infection in CS but was barely detectable in CHB." (PMID 27197554, 2016). "During the evolution of the infection, the number of IL-4-producing CD8+ T-cells increased in both infections." (PMID 27073297, 2016). "Restricting Il4 deficiency to ILC2s in vivo revealed an important role of ILC2s for the differentiation of IL-13+ and IL-5+ TH2 cells following infection with H. polygyrus." (PMID 26883724, 2016). "On day 61 post-infection and post-treatment, Mentha 60 experimental group showed a 53.5% decrease in IL-4 levels when compared to the positive control group." (PMID 27378927, 2016). "The rapid up-regulation of the expression of SAP1, hepcidin and CATH1 by both IL-4/13A and IL-4/13B2 suggests a role of these type-2 cytokines in the resolution of infection." (PMID 26870894, 2016). "It is noteworthy that reinfected animals exhibited significantly higher levels of IL-4 until the beginning stage (fourth day) of the last infection." (PMID 26814713, 2016). "MCP-1 can recruit monocytes, T-lymphocytes and dendritic cells to the inflammatory sites of tissue injury or infection, and IL-4 functions as a potent stimulator for MCP-1 expression." (PMID 27121311, 2016). "This revealed 13 mediators of inflammation that correlated with infection status, which were, in order of strength of significance, IL-4, IL-5, IL-7, IL-15, IFN-α, IL-12, IFN-γ, IL-17, IL-1Ra, TNF-α, IL-1β, IL-10, and IL-2." (PMID 27418744, 2016). "Concerning the possible consequences of IL-13 reduction by BPA, it is well known that IL-13, together with IL-4, orchestrate type-2 immunity, inducing host protection, with defense mechanisms against parasites and controlling infection." (PMID 27509021, 2016). "The results showed that the concentration of IL-2 and IL-17 was statistically increased in the groups treated with JS after infection, whereas the level of IL-4 was significantly decreased." (PMID 27558409, 2016). "Titers of IL-4 decreased after infection with both Listeria but it recovered earlier in LI infected mice." (PMID 27375558, 2016). "Infection via the footpad is known to elicit an early burst of IL-4 mRNA and significant levels of Th2 cytokines by day 7 of infection." (PMID 27992545, 2016). "The analyses of T helper cell differentiation during infection of IL-4-reporter mice confirmed previous reports showing that Tfh cells can express IL-4 and demonstrated that the majority of IL-4 production is localized to the B cell follicle." (PMID 31557986, 2016). "Paradoxically, despite reduced IL-4 detected in sera and reduced production of IgG1 after infection, Il21r−/− mice harbor increased amounts of the antibody isotype IgE." (PMID 31557986, 2016). "A series of studies identified that basophils were an important source of IL-4 for TH2 differentiation during murine infection with the rat parasite Nippostrongylus brasiliensis." (PMID 26883724, 2016). "VHSV exposure resulted in a significant increase in IL-4/13B1 and B2 expression in the kidney during the early stages post infection (eg 1 to 5 days for IL-4/13B1, and 1-4 days for IL-4/13B2) that peaked at day 3 with a 26.3-fold increase for IL-4/13B2." (PMID 26870894, 2016). "Titers of TNF-α, IL-6, IL-12, and IL-4 after infection changed at same level between LI and LM infections." (PMID 27375558, 2016). "Secondary infection induced a rapid increase in the expression of IL-4, IL-6 and IL-13 from 2 wpsi and beyond." (PMID 27658962, 2016). "Th2 cells produce IL-4, IL-5, and IL-13 that stimulate B cells and control extracellular infections through the secretion of antibodies." (PMID 26808410, 2016).
infection (continued). "IL-4 titer in the spleen kept declining during the course of LM infection, whereas titers for LI infection declined first and then returned to the level of naive control group since 5 dpi." (PMID 27375558, 2016). "The levels of proinflammatory cytokines like TNF-α and interleukin (IL)-1β and Th2 cytokines like IL-10 and IL-4 were measured by reverse transcription qPCR (RT-qPCR) in the liver, lung and spleen of the infected mice at day 7 post-infection." (PMID 26902658, 2016). "In the livers of animals infected with HA-MARV, the pro-inflammatory cytokines TNF-α and IL-6, as well as the Th2 cytokines IL-4 and IL-5 and the Th1 cytokine IL-12, were all elevated early before decreasing over the course of infection." (PMID 27976688, 2016). "Negatively selected CD4+ T cells from WT and ΔdblGATA brains after 1 and 2 wks of infection were compared at the transcript level for Il4 and Gata3 (a transcription factor involved in polarizing T cells towards Th2 phenotype) expression." (PMID 27332553, 2016). "The level of IL-4 increased in the group of mice that was immunized with various combinations such as archae-Rv3203 and EC-Z + archae-Rv3203 post challenge with infection." (PMID 27023750, 2016). "It is still unclearwhether IL-4 and IFN-γ are responsible for susceptibility or resistance, respectively,to infection withP." (PMID 26517657, 2015). "Cytokine mRNA quantification showed increased levels of IFNγ, TNFα, IL-4, IL-6, and IL-12 during infection." (PMID 26481427, 2015). "Infection with stimulation by GM-CSF or GM-CSF plus IL-4 was mainly with BaL+ viruses, and at similar levels to that observed without stimulation." (PMID 26055104, 2015). "The cytokines IL-4, IL-5 and IL-10 are thought to balance the pro-inflammatory milieu generated in an infection to keep the host tissue safe from its own inflammatory immune responses." (PMID 26566996, 2015). "Th2 cytokines, IL-4 and IL-10, are elevated starting approximately 2 weeks after infection and peak at three weeks following infection during the resolution stage." (PMID 26697208, 2015). "At the initial phase of infection, monocytes are effectively recruited to the inflammation site, being stimulated by cytokines such as IFNγ and IL-4 to differentiate into macrophages." (PMID 26135738, 2015). "In WT mice, when the concentrations of IFNγ and TNFα increase during clearance of infection, the concurrent induction of IL-4 and IL-6 thus appears to protect the mitochondrial function of the colonic epithelium from further damage." (PMID 26481427, 2015). "These factors include OSM, IL-4 (gene up-regulated on day 1 post infection) and MIF (macrophage migration inhibitory factor) that induces P- and E-selectin and vascular cell adhesion molecule 1 (VCAM-1)." (PMID 25719526, 2015). "On the other hand, Th2-like cytokines such as IL-4, IL-5 and IL-13 are predominant in immune responses to the chronic phase of infection which induce alternative activation of MΦs and upregulate the ADCC response." (PMID 26578348, 2015). "As IFNγ and TNFα levels increase during clearance of infection, the concomitant increase in IL-4 and IL-6 protects mitochondrial function." (PMID 26481427, 2015). "The expression levels of il2, il4, and ifngamma were below the detection limit in all tissues in this round of infection experiments." (PMID 26146835, 2015). "Neutralizing IL-33 during primary infection in neonates resulted in significant reductions in Th2 and multifunctional Th (mTh; IFNγ+, IL-4+) cells upon reinfection (α-IL-33+NRR)." (PMID 26473724, 2015). "The presence of both IL-4 and IL-6 during the clearance phase of infection, when TNFα and IFNγ levels are exceedingly high, protects the colonic epithelial surface against more detrimental damage." (PMID 26481427, 2015). "The present study showed that the polyproteins vaccine plus saponin induced a low production of IL-4 and IL-10 before infection, which was maintained in low levels after challenge." (PMID 26367128, 2015).
infection (continued). "FI-RSV-immunized mice on day 3 post-infection exhibited a significant (p<0.01) reduction in both IL-4 and IL-13 protein amounts in the lung." (PMID 25769044, 2015). "The cytokine environment during the course of infection was different in IFNγ−/− compared to WT mice, mainly with regards to that IL-4 and IL-6 were upregulated already by day 10 post infection (3-fold vs 20-fold)." (PMID 26481427, 2015). "Results revealed that vaccinated mice in pre- or post-infection situation exhibited the lowest IL-4/IFN-γ mRNA ratios." (PMID 26053794, 2015). "Consistent with the observation at primary infection, rA2-19F reinfection increased the frequency of IL4 expressing CD4+ T cells (15.54 ± 1.70 vs. 8.33 ± 0.82 %) and decreased the frequency of IFNγ expressing CD4+ T cells (31.46 ± 2.41 vs 48.08 ± 3.24 %)." (PMID 26231396, 2015). "At the peak of clinical signs, 7 days post infection, the calves in study 2 also demonstrated an increase of IFNγ and minimal amounts of IL-4 in BAL supernatant, which agrees with previously reported responses to primary BRSV infection in calves." (PMID 25890239, 2015). "Macrophages, eosinophils and lymphocytes gathered at the site of inflammation and Th2-type cytokine secretion such as IL-4, IL-5, IL-10, and IL-13 were increased under the stimulation of worm antigen in the late infection phase." (PMID 26070790, 2015). "The proportion of Th2 (CD4+IL-4+) cells remained low at 3 days post-infection but then significantly increased and reached a maximum (16.66% of total CD4+ lymphocytes) at 5 days post-challenge." (PMID 26230498, 2015). "The production of IL-4 in early infection inhibits protective Th1 cell differentiation most likely by either direct or indirect inhibition of IFN-γ production." (PMID 25886737, 2015). "Active infection favours induction of a Th2 skewed immune response characterised by markedly elevated levels of IL-4 and IL-10." (PMID 26377900, 2015). "The up-regulated expression of IL-4, IL-5, IL-10, and IL-13 showed Th2 cell predominance in immunopathological reactions at late infection phase in response to infection by A. cantonensis." (PMID 26070790, 2015). "Nevertheless, treatment of infected mice with saponin (Inf/Sap) alone resulted in a similar IL-4/IFN-γ mRNA-ratio as found in animals that received rEmP29-Sap at 1 month post-infection." (PMID 26053794, 2015). "Cells from diabetics produced higher levels of IL-4 and of both, IL-4 and IL-10 as well as granulocyte-macrophage colony-stimulating factor (GM-CSF) on the first and third day post-infection, respectively." (PMID 25909658, 2015). "IFNγ and IL-12 mRNA were upregulated at all time points, whereas TNFα and IL-4 upregulation started at day 14 and IL-6 mRNA only increased at day 19 post infection." (PMID 26481427, 2015). "High concentrations of Th2 cytokines, IL-4 and IL-10 were observed in infection control group (P < 0.001) in comparison to naïve mice and a profound decline in IL-10 and IL-4 levels was witnessed in ALE and ASE treated groups (P < 0.01)." (PMID 25884649, 2015). "As blockade of IL-4 prior to infection with Lesihmania major induces normal parasite specific Th1 responses in IL-27Rα KO mice, the susceptibility in these mice is not due to a defect in Th1 immunity, but rather a consequence of accelerated Th2 responses." (PMID 25633106, 2015). "In this work we show that F. hepatica glycoconjugates are involved in the induction of high levels of IL-10 and IL-4 as well as in the reduction of IFNγ production by splenocytes during infection." (PMID 26720149, 2015). "During the process of infection, expression level of IL-21 produced by Tfh cells is much higher than IL-4." (PMID 26503442, 2015). "In order to evaluate the role of NKT cells in the present model, we performed cytokine staining (IFNγ, TNFα and IL-4) three days post infection." (PMID 26296209, 2015).
infection (continued). "Infection with C. rodentium alone led to decreases in complex I and IV activities that were counteracted by IL-4 (−58% to −13%, P < 0.05, and −55% to −14%, P < 0.001)." (PMID 26481427, 2015). "Consistent with the presence of Th2 cells, the mRNA expression of its prototypical cytokine Il4 increased significantly at 5 days post-infection." (PMID 26230498, 2015). "We note that IL-12 and IFNγ (a Th1 cytokine response), and IL-10, IL-4, IL-13 or IL-5 (Th2 cytokine response) were either down-regulated during the latter phase of infection or remained unchanged." (PMID 25719526, 2015). "Our observation that IL-4-induced Eomes+ innate CD8+ T cells are more effective at controlling the CL–13 infection than Eomes- conventional CD8+ T cells raises a question regarding the underlying mechanism." (PMID 26452143, 2015). "ALA patients as well as AC subjects had significantly higher IL-4 levels than the E. dispar-infected individuals, suggesting that asymptomatic infection with E. histolytica induces a considerable immune response." (PMID 25420932, 2014). "In this study, the expression profiles of the studied cytokines in terms of fold change (IFN-γ > IL-4 > IL-12p40 > TNF-α ≥ IL-10) were consistent with those demonstrated in previous studies of early infection when foetal death prevailed." (PMID 24479988, 2014). "Here, we have shown the increased production of IFN-γ and decreased production of IL-4 and IL-10 in spleen cells after seven days of infection that indicates the systemic Th1 polarization induced by LaSP-Ex intranasal vaccination." (PMID 25239157, 2014). "We know that the M2-polarizing cytokine IL-4 is present within the hepatic milieu during infection, and previous reports indicate that hepatic macrophages are M2 activated in this setting." (PMID 25144366, 2014). "Although IL-10 levels remained comparable to controls, the levels of IL-4 produced in alum + LAg immunized mice were significantly enhanced at 4 months post-challenge infection (p < 0.001)." (PMID 24428931, 2014). "Saliva was demonstrated to enhance pathology, infection level, and the production of Th2 cytokines (IL-4 and IL-10) in naïve mice." (PMID 25275509, 2014). "The MC from pelvic lymph nodes of the infection group produced significantly less IL-4 than the MC of the control group." (PMID 25252649, 2014). "Infection caused by L. guyanensis accounted for 73% of the cases and patients with this parasite also showed higher concentrations of IL-2, IFN-γ, IL-4, and IL-17 when compared to infection by L. amazonensis." (PMID 25295285, 2014). "Among these cytokines, levels of IL-9 were significantly increased upon infection and decreased after treatments, showing a positive correlation with level of IL-4." (PMID 24799769, 2014). "Naïve mice exposed to saliva during infection, however, had significantly higher IL-4 levels than control mice exposed only to the pathogen (estimate 1.7196, p value 0.0185)." (PMID 25275509, 2014). "Prior infection with L. major increased expression of LIGHT in macrophages treated with IFN-γ plus IL-4." (PMID 25110400, 2014). "IL-4 cytokine levels peaked with the onset of microfilaremia at 60 dpi, whereas IL-5, IL-13 and IL-25 levels increased with the duration of infection." (PMID 24663956, 2014). "For some other infection models, including a fungal pathogen (e.g. Candida albicans), it was shown, that IL-4 can be involved in the induction of Th1 immune responses and elevated IFN-γ production." (PMID 24475277, 2014). "Paradoxically, IL-4 administration during early infection enhances IL-12 production by DCs and establishes resistance to L. major in susceptible BALB/c mice." (PMID 25126585, 2014). "The observed difference in levels of transcripts for IL-4 and IL-5 in the abomasal mucosa following infection of yearlings with T. circumcincta is consistent with studies of H. contortus infection of sheep and O. ostertagi infection of cattle." (PMID 24712712, 2014).
infection (continued). "Th-1 cytokines such as IFN-γ, TNF-α, and IL-2 favor resistance to infection while IL-4, IL-10 and IL-13 mediate disease progression and parasite persistence." (PMID 25500571, 2014). "Partial depletion of CD4 T cells, or the administration of neutralizing anti-IL-4 antibody, close to the time of infection with 106 parasites, modulates the response from a Th2 to Th1 mode, resulting in resistance." (PMID 24684592, 2014). "Here, we opted to focus on IL-6, a cytokine that can directly affect macrophages, exert a variety of pro-inflammatory effects, and which is produced along with IL-4+IL-13 following infection with helminth parasites." (PMID 24736635, 2014). "In this study, we chose to investigate the mechanism of regulation of IL-4 and IL-12 expression following infection of lymphocytes from pig spleen with PCV2." (PMID 24841678, 2014). "rCPA and rCPB immunizations although showed heightened IFN-γ and IL-12 expression, also enhanced expression of disease promoting cytokines like IL-4 and IL-10 mRNAs after infection, which perhaps limited their vaccine efficacy." (PMID 25144181, 2014). "We wanted to investigate DNA methylation of Ifng and Il4 in a physiologically relevant infection setting." (PMID 24578067, 2014). "Further, both macrophage proliferation and numbers are reduced in IL-4−/− and IL-4Rα−/− mice in all infection models tested, emphasizing the central role of IL-4 in driving macrophage accumulation during infection." (PMID 25319331, 2014). "In this study, changes in IL-4 and IL-12 expression and the regulatory mechanisms involved were investigated in piglet lymphocytes after infection with PCV2." (PMID 24841678, 2014). "In our study, after infection with S. japonicum for three weeks, cytokines (such as IL-4, IL-5, IL-6, IL-13, TNF-α and GM-CSF) in the sera of M. fortis were significantly increased, whereas cytokine levels of the BALB/c mice were much lower (data not shown)." (PMID 24886088, 2014). "Parasitic enteric nematodes induce a type 2 immune response characterized by increased production of Th2 cytokines, IL-4 and IL-13, and recruitment of alternatively activated macrophages (M2) to the site of infection." (PMID 24465430, 2014). "These experiments implicate that deficiency of IL-4 contributes to mild cardiovascular and renal effects and the protective role of IL-4 is more pronounced during infection." (PMID 24904596, 2014). "Next, we examined infection of tonsil cells cultured with IL-4, finding that CD62L was reduced in these cells as well, though not as strongly as in peripheral blood cells." (PMID 25330112, 2014). "Parasite numbers were counted in blood and skeletal muscle at different times post-infection, and real time-PCR expression levels of the cytokines IL-12, IL-4, IL-10, IFN-γ, and TNF-α were evaluated." (PMID 24991553, 2014). "The severe infection group had a higher level of IL-4 than all other groups, and the silent and minor infection groups had a higher level of IL-4 relative to the control group." (PMID 24646014, 2014). "Th1 type cytokines (IFN-γ, TNF-α) are involved in immune activation and then the injury of HBV antigen expressed hepatocytes, while Th2 type cytokine productions (IL-10, IL-4) inhibit immune reaction and involved in the persistence of infection." (PMID 25144199, 2014). "Significant differences between infected groups in IFN-γ and IL-4 levels were observed only in the first and second week of infection." (PMID 24479988, 2014). "IL-4, IL-10 and IL-12a expression in the thymocytes of LPi mice were almost undetectable due to an interaction of low protein diet and infection, whereas TGF-β was increased due only to the effect of low protein diet." (PMID 25535967, 2014). "Along with the need for high concentrations of IL-4 19, these data strongly suggest a requirement for cognate T-helper interactions to initiate macrophage proliferation in the infection context." (PMID 25319331, 2014).